KMT2D (lysine methyltransferase 2D)
Description:
Histone methyltransferase that catalyzes methyl group transfer from S-adenosyl-L-methionine to the epsilon-amino group of 'Lys-4' of histone H3 (H3K4). Part of chromatin remodeling machinery predominantly forms H3K4me1 methylation marks at active chromatin sites where transcription and DNA repair take place. Acts as a coactivator for estrogen receptor by being recruited by ESR1, thereby activating transcription.
Synonyms: ALR; MLL2; MLL4; CAGL114; AAD10; BCAHH; KABUK1; KMS; TNRC21
Tractability: Small molecule: a structure with a bound ligand is known. Antibody: the Human Protein Atlas places it where antibodies can reach. PROTAC: UniProt records ubiquitination sites on it; ubiquitination databases record sites on it; its protein half-life has been measured.
Target class: Writer; Protein methyltransferase; Epigenetic regulator
Gene: Protein-coding gene on chromosome 12 (49,018,975 to 49,060,794, reverse strand). Ensembl gene ENSG00000167548.
Subcellular location: Nucleus
Subcellular location (Human Protein Atlas): Cytosol; Plasma membrane; Nucleoplasm
Pathways (Reactome):
Gene expression (Transcription): Epigenetic regulation of gene expression by MLL3 and MLL4 complexes; Formation of WDR5-containing histone-modifying complexes; MLL4 and MLL3 complexes regulate expression of PPARG target genes in adipogenesis and hepatic steatosis; RUNX1 regulates genes involved in megakaryocyte differentiation and platelet function
Chromatin organization: PKMTs methylate histone lysines
Developmental Biology: Activation of anterior HOX genes in hindbrain development during early embryogenesis
Disease: Loss of Function of KMT2D in MLL4 Complex Formation in Kabuki Syndrome
Gene Ontology:
Molecular function: histone H3K4 monomethyltransferase activity; protein binding; transcription cis-regulatory region binding; DNA binding; histone H3K4 methyltransferase activity; transcription coactivator activity; DNA-binding transcription activator activity, RNA polymerase II-specific
Biological process: positive regulation of cell population proliferation; positive regulation of intracellular estrogen receptor signaling pathway; positive regulation of transcription by RNA polymerase II; response to estrogen; heterochromatin formation; oocyte growth; oogenesis; regulation of DNA-templated transcription
Cellular component: MLL3/4 complex; nucleus; nucleoplasm; histone methyltransferase complex
Genetic constraint (gnomAD): Loss-of-function variants: 54 observed, 480.55 expected, observed/expected ratio (o/e) 0.11, 90% interval 0.089 to 0.14. The upper end of that interval is the gene's LOEUF score, 0.14, which puts it in group 1 of 6, group 1 being the genes least tolerant of losing a copy. Missense variants: 6,024 observed, 7,115.4 expected, observed/expected ratio (o/e) 0.85, 90% interval 0.83 to 0.87. Synonymous variants: 2,974 observed, 2,892.7 expected, observed/expected ratio (o/e) 1.03, 90% interval 1 to 1.06.
Gene-disease validity (ClinGen):
ClinGen rates the evidence that KMT2D causes each of these diseases.
Kabuki syndrome 1 (autosomal dominant): Definitive.
Cancer hallmarks: cell replicative immortality (promotes); invasion and metastasis (promotes); proliferative signalling (promotes); change of cellular energetics (promotes)
Homologues: Orthologues: chimpanzee KMT2D (99% identical), macaque KMT2D (98% identical), dog KMT2D (94% identical), rabbit KMT2D (90% identical), mouse Kmt2d (89% identical), rat Prkag1 (88% identical), guinea pig KMT2D (88% identical), zebrafish kmt2d (27% identical), Caenorhabditis elegans set-16 (12% identical), Drosophila melanogaster trr (11% identical), Drosophila melanogaster ash1 (4% identical), Caenorhabditis elegans met-1 (3% identical), and 14 more. Paralogues in human: KMT2C (31% identical), KMT2A (10% identical), KMT2B (8% identical), SETD1B (6% identical), SETD1A (5% identical), ASH1L (4% identical), NSD1 (4% identical), EHMT1 (3% identical), NSD3 (3% identical), EHMT2 (3% identical), NSD2 (3% identical), SETBP1 (3% identical), and 7 more.
Diseases named in the same sentence as KMT2D in open-access papers:
KMT2D is named in the same sentence as 285 diseases in open-access papers, as found by Europe PMC text mining. Sharing a sentence is not in itself a finding about the gene and the disease. The quoted sentences say what the papers report.
Kabuki syndrome (137 papers, 2013 to 2026). Kabuki syndrome (KS) is a multiple congenital anomaly syndrome characterized by typical facial features, skeletal anomalies, mild to moderate intellectual disability and postnatal growth deficiency. "Approximately 80% of mutations in individuals with Kabuki syndrome have predominant mutations specifically in the KMT2D gene." (PMID 41341998, 2025). "KMT2D loss-of-function mutations are the genetic cause of Kabuki syndrome, a congenital developmental disorder that affects cardiovascular development." (PMID 40869273, 2025). "Among them, Kabuki syndrome is a syndromic DD/ID disorder characterized by a distinctive facial gestalt, caused by LoF pathogenic variants in the KMT2D and KDM6A genes." (PMID 40004505, 2025). "One patient (P7) was diagnosed with Kabuki syndrome due to a pathogenic variant at the KMT2D gene (c.5993A > G, p.Tyr1998Cys), which was previously reported." (PMID 41155848, 2025). "Kabuki syndrome is caused by mutations in the KMT2D gene, which encodes an H3K4 histone methylase that promotes active gene transcription, or in the KDM6A gene, an X-linked histone H3K27 demethylase." (PMID 39941150, 2025). "Although the link between KMT2D and SLE remains largely unexplored, KMT2D loss has been implicated in the autoimmune phenotype observed in Kabuki syndrome." (PMID 40999523, 2025). "This study reports on a 16-year-old male patient diagnosed with type I Kabuki syndrome following the identification of a de novo mutation, c.15535C>T (p.Arg5179Cys), in the KMT2D gene." (PMID 40125530, 2025). "For example, haploinsufficiency of KMT2D has been identified as a mutation responsible for Kabuki syndrome, a congenital disorder characterized by growth and developmental delays affecting multiple organ systems, including the cardiovascular system." (PMID 40869273, 2025). "Kabuki syndrome is caused by mutation in the KMT2D gene, encoding for a ubiquitously expressed histone-lysine N-methyltransferase, which monomethylates lysine 4 of histone H3 (H3K4me1) of distal enhancers, leading to transcriptional activation." (PMID 40021842, 2025). "Collectively, these studies underscore the critical role of KMT2D variants in the pathogenesis of cardiac malformations in patients with Kabuki syndrome and provide molecular insights linking specific genetic variants to distinct cardiac phenotypes." (PMID 38667491, 2024). "In total, 22 (95.7%) of 23 patients with Kabuki syndrome presented with pathogenic variants on molecular analysis of the KMT2D gene." (PMID 38667491, 2024). "NDUFB5 encodes a subunit of complex I, which plays a role in oxidative phosphorylation, a pathway known to be dysregulated in KMT2D-deficient lung adenocarcinomas and Kabuki syndrome patients." (PMID 39578878, 2024). "TFB1M is a mitochondrial transcription specificity factor that maintains homeostasis of oxidative phosphorylation and glycolysis, pathways that have been shown to be dysregulated in KMT2D-deficient lung cancers, epithelial cells, and Kabuki Syndrome patients." (PMID 39578878, 2024). "Individuals with Kabuki syndrome present with immunodeficiency; however, how pathogenic variants in the gene encoding the histone-modifying enzyme lysine methyltransferase 2D (KMT2D) lead to immune alterations remain poorly understood." (PMID 38765012, 2024). "About 60–75% of cases with clinical diagnosis of Kabuki syndrome have a disease-causing variant in KMT2D, encoding a histone-lysine N-methyltransferase 2D protein." (PMID 38206414, 2024). "The current study aimed to analyze the prevalence, anatomic types, and genetic characteristics of CHDs in 23 patients with Kabuki syndrome and the pathogenic variants in the KMT2D gene." (PMID 38667491, 2024). "Together, these data show that the targeted loss of Kmt2d in the T-cell lineage recapitulates several distinct features of Kabuki syndrome-associated immune deficiency and implicates epigenetic mechanisms in the regulation of integrin signaling." (PMID 38765012, 2024).
Kabuki syndrome (continued). "Kabuki syndrome (KS), mainly caused by lysine methyltransferase 2D (KMT2D; OMIM 602113) variants, is a rare congenital disorder with multi-organ deficiencies." (PMID 39139573, 2024). "In 2010, pathogenic variants in the KMT2D gene (MLL2) were found to be the primary cause of Kabuki syndrome, accounting for 55–80% of all cases." (PMID 38667491, 2024). "KS1 accounts for up to 75% of Kabuki syndrome cases, and originates from heterozygous, typically de novo, pathogenic variants in KMT2D, which encodes a histone lysine methyltransferase that mono-, di-, and tri-methylates H3K4." (PMID 38857303, 2024). "Kabuki Syndrome (KS) encompasses a spectrum of clinical manifestations, primarily attributed to pathogenic variants in the KMT2D gene." (PMID 39104744, 2024). "We detail the macular phenotype in two unrelated patients with Kabuki syndrome due to de novo nonsense variants in KMT2D, one novel." (PMID 38206414, 2024). "Here, we report two additional cases of macular dystrophy in two unrelated patients with Kabuki syndrome 1 and de novo nonsense variants in KMT2D, one already described and the other one novel." (PMID 38206414, 2024). "Herein we present a case series of ten Kabuki Syndrome patients with confirmed KMT2D-missense pathogenic variants." (PMID 39104744, 2024). "The second fetus with skeletal anomalies (case 1) was diagnosed with Kabuki syndrome as a result of a de novo stop mutation in KMT2D (OMIM# 147920)." (PMID 36900003, 2023). "Variants in KMT2D cause Kabuki syndrome, a rare congenital disease with multiple anomalies, in which around 70% of patients present with congenital heart defects, with a unique predilection for left-sided obstructive lesions." (PMID 38139143, 2023). "Beyond their roles in cancer and viral receptor expression, mutations in KDM6A and KMT2D have been identified in Kabuki syndrome, which is characterized by developmental delay." (PMID 37410700, 2023). "Kabuki syndrome (KS) is a chromosomal abnormality disease that has its origin in the mutation of lysine methyltransferase 2D(KMT2D)." (PMID 37641008, 2023). "Sequencing analysis for Kabuki syndrome panel detected a nonsense variant in the KMT2D (NM_003482.3) gene: c.8974G>T, p.Glu2992Ter." (PMID 37360370, 2023). "Variants in KMT2D cause Kabuki syndrome, a rare congenital disease marked by multiple anomalies, including short stature, distinctive facial features, intellectual disability, persistent fingertip pads, and skeletal abnormalities." (PMID 37504561, 2023). "Kabuki syndrome (KS) is a rare multisystemic disease due to mutations in the KMT2D or KDM6A genes, which act as epigenetic modulators of different processes, including immune response." (PMID 37360370, 2023). "KMT2D, the gene mutated in Kabuki syndrome, has been suggested to function in the same chromatin modification machinery." (PMID 36568983, 2022). "Mutations in KMT2D (also an epigenetic writer gene) cause Kabuki syndrome, as do mutations in KDM6A (an eraser gene involved in demethylation of histones) demonstrating the complexity of epigenetic programming." (PMID 35860466, 2022). "Kabuki syndrome (KS) is a rare neuro-developmental disorder caused by variants in genes of histone modification, including KMT2D and KDM6A." (PMID 36292647, 2022). "This was relevant to three cases with Kabuki syndrome caused by KMT2D gene mutation, one case with KAT6A gene mutation, and one case with a 5.05-Mb draft genome sequence at chr10:130378377–135427935 q26.2–q26.3." (PMID 35612621, 2022). "Included were three cases with Kabuki syndrome caused by the KMT2D gene, one case with the KAT6A gene, and one case with a 5.05-Mb draft genome sequence at chr10:130378377–135427935 q26.2–q26.3." (PMID 35612621, 2022). "The Kabuki syndrome can be caused by the loss of function of KMT2D (also called MLL2) or KDM6A (also called UTX)." (PMID 35997367, 2022).
Kabuki syndrome (continued). "Another interesting finding was that four of the five sequence variants occurred in KMT2D, the causative gene of Kabuki syndrome-1 (OMIM:147920)." (PMID 36151134, 2022). "We also identified two other variants in this line before the non-recombinant region was fully defined; a 27 bp inframe deletion in the Kmt2d gene which underlies Kabuki syndrome in humans, and a missense mutation in the gene Muc13." (PMID 35296311, 2022). "Kabuki syndrome is a rare genetic condition associated with two gene mutations: KMT2D in the majority of cases and KDM6A less frequently." (PMID 40041237, 2022). "Kabuki syndrome (KS) is a rare genetic disorder caused by mutations in the histone modifier genes encoding histone H3 lysine 4 methyltransferase (KMT2D) and histone H3 lysine 27 demethylase (KDM6A) (OMIM: #147920 and #300867)." (PMID 35992033, 2022). "KMT2D alterations are the main cause of Kabuki syndrome, a congenital intellectual disability with genitourinary anomalies among other additional features." (PMID 34803902, 2021). "In fact, impaired H3K4 methyltransferase activity of KMT2D variants, another Kabuki syndrome associated gene product, is in part due to disruption of WRAD complex formation, which further associates and stimulates the COMPASS catalytic activity." (PMID 33546721, 2021). "Kabuki syndrome (KS), a rare multisystemic immune disorder, was diagnosed in P13 carrying the novel heterozygous E1738* mutation in KMT2D gene." (PMID 35058929, 2021). "KMT2D is a major causative gene of Kabuki syndrome with teeth dysplasia including missing teeth and conical teeth." (PMID 34724040, 2021). "In our findings, the most frequently mutated gene of epigenetic regulators was KMT2D, which encodes histone methyltransferase for methylates the Lys-4 position of histone H3, and its mutation can cause Kabuki syndrome, an autosomal dominant disease." (PMID 32164600, 2020). "For this purpose, we used Kmt2d knockout MEFs and fibroblasts from Kabuki syndrome-affected patients harboring KMT2D heterozygous pathogenic variants." (PMID 32668765, 2020). "The protein encoded by KMT2D has been shown to be a transcriptional regulator of the beta-globin and estrogen receptor genes and is reported to be a cause of Kabuki syndrome." (PMID 32278351, 2020). "Mutation of KMT2D is associated with Kabuki syndrome (OMIM #147920), a rare developmental disorder which includes CHD as part of a wide phenotypical spectrum." (PMID 32859249, 2020). "In Xenopus, Kmt2d loss of function mutations recapitulate Kabuki syndrome and demonstrate that this methylase is required for dispersion of the migrating neural crest cells." (PMID 33182738, 2020). "Mutations in KMT2D or KMD6A are associated with Kabuki Syndrome, which shares characteristics to CHARGE syndrome including microphthalmia and coloboma." (PMID 33182738, 2020). "Mutations in KMT2D are the main cause of the genetic disease Kabuki syndrome, and several mutations in the 39th exon have been found in Kabuki patients." (PMID 32337102, 2020). "Mutations in KMT2D have been known to cause Kabuki syndrome (OMIM: #147920) in an autosomal dominant manner, commonly resulting in heart defects and renal malformations consistent with the presentation of this fetus." (PMID 31475041, 2019). "Mutations in the KMT2D gene are reported mainly in association with Kabuki syndrome; thus, it is possible that the refractory epilepsy and developmental delay observed in this patient were associated with the KMT2D mutation." (PMID 31689829, 2019). "We then examined data from Kabuki syndrome patients carrying pathogenic variants in the KMT2D gene, which also encodes a lysine histone methyltransferase." (PMID 31160375, 2019). "Kabuki syndrome is caused by loss-of-function mutations in KMT2D, a major mammalian H3K4 mono-methyltransferase." (PMID 31409373, 2019).
Kabuki syndrome (continued). "To exemplify this, we observed a DDD participant with a validated diagnostic child-PZM LOF variant in KMT2D who exhibited an intermediate biomarker phenotype for a published DNA methylation signature for Kabuki syndrome caused by mutations in KMT2D44." (PMID 31278258, 2019). "KMT2D gene alterations were determined to be diagnostic in two separate individuals, thus, Kabuki syndrome was the most common diagnosis." (PMID 30293990, 2019). "We tried to answer this question by supplying a large cohort of such diseases, including 44 patients with Kabuki syndrome that results from mutations in KMT2D (another regulator of the H3K4) to our classification model for KDM5C epi-signature." (PMID 29456765, 2018). "KMT2D mutations are known to be associated with Kabuki syndrome, which is characterized by cranial and facial malformations, growth deficiency, short stature, and skeletal malformations." (PMID 29567674, 2018). "Germline mutations in KMT2D underlie the molecular pathogenesis of 52–76% of patients with Kabuki syndrome." (PMID 29321794, 2017). "Kabuki syndrome patients carry truncating mutations in KMT2D, which are predicted to result in haploinsufficiency." (PMID 26932671, 2016). "Kabuki syndrome is a complex developmental disorder including CHD caused by mutation in KMT2D, a histone methyltransferase." (PMID 27670201, 2016). "Studies with large cohorts of patients indicate that KMT2D gene mutations can be detected in half to three-fourths of patients with clinical diagnoses of Kabuki syndrome." (PMID 25896430, 2015). "Later, mutations in the KDM6A gene, which encodes a histone demethylase that interacts with KMT2D, were identified (Kabuki syndrome 2, OMIM 300867)." (PMID 25896430, 2015). "Similarly, there is a close resemblance between the DNAm signatures associated with pathogenic variants in ASXL2 and ASXL1 causing Shashi-Pena and Bohring-Optiz syndromes respectively, and between KDM6A and KMT2D variants causing Kabuki syndrome." (PMID 39843918, 2025). "Variations in KMT2D are associated with Kabuki syndrome (KS)." (PMID 40909434, 2025). "Moreover, a recent study aimed to characterize the molecular impact of KMT2D variants on the epigenetic and transcriptional landscapes of Kabuki Syndrome." (PMID 39104744, 2024). "KMT2D mutations have also been observed in Kabuki syndrome patients." (PMID 39117610, 2024). "In addition, mutations in KMT2D have been associated with Kabuki syndrome, a congenital disorder marked by multiple malformations, the most prominent of which are distinctive craniofacial features." (PMID 38139143, 2023). "Heterozygous gene inactivating mutations in KMT2D cause Kabuki syndrome in humans." (PMID 37463940, 2023). "KDM6A and KMT2D are frequently mutated in Kabuki syndrome and multiple cancers." (PMID 37410700, 2023). "KMT2D is a major cause for Kabuki syndrome (OMIM:147920), in which CHD is predominantly presented." (PMID 35518361, 2022). "Previous studies have reported that KMT2D mutations can lead to Kabuki syndrome." (PMID 35361250, 2022). "Lysine methyltransferase 2D (KMT2D), as one of the key histone methyltransferases responsible for histone 3 lysine 4 methylation (H3K4me), has been proved to be the main pathogenic gene of Kabuki syndrome disease." (PMID 34724040, 2021). "Kabuki Syndrome (KS) is a human congenital disorder with mutations in KMT2D." (PMID 31479440, 2019). "Kabuki syndrome is caused by a heterozygous mutation in the KMT2D or KDM6A genes." (PMID 29914387, 2018).